MIF (macrophage migration inhibitory factor)
Diseases named in the same sentence as MIF in open-access papers (continued):
Sharing a sentence is not in itself a finding about the gene and the disease.
asthma (continued). "OVA-induced asthma model revealed significantly higher MIF concentration in the lung tissues than the control group." (PMID 37674165, 2023). "In asthma, MIF induces CCl2, CXCR2, and CXCR4 expression through the ERK / MAPK / P38 / Rho A GTPase pathway." (PMID 37422662, 2023). "In the present study, we elucidated the role and mechanisms of MIF in promoting airway remodeling in asthma." (PMID 37674165, 2023). "We showed that osthole inhibited airway inflammation, airway remodeling and macrophage activation in our asthma model, and MIF expression was also suppressed in the osthole group." (PMID 33828480, 2021). "Mechanistically, the pathological role of PI3Kγ in asthma implicates the release of inflammatory cell mediators, including macrophage migration inhibitory factor (MIF) and the T-helper type II cytokine Interleukin-13 (IL-13)." (PMID 33821232, 2021). "Magalhaes and colleagues also reported a reduction in AHR (Penh) in MIF knockout mice in response to metacholine in an OVA model of asthma." (PMID 26752192, 2016). "However, we are the first to demonstrate enhanced VEGF production from MSCs licensed with human MIF, a clinically relevant proinflammatory cytokine in a range of inflammatory diseases including asthma." (PMID 39502000, 2025). "Furthermore, MIF’s dual role in different types of inflammation (Th2-related in asthma and possibly Th1 in other conditions) indicates that therapies must be carefully tailored to avoid unintended consequences." (PMID 39337534, 2024). "MIF expression was found to be higher in bronchoalveolar lavage of patients with asthma." (PMID 39337534, 2024). "Collectively, these studies suggest that MIF plays a crucial role in the pathophysiology of asthma." (PMID 37674165, 2023). "Furthermore, in OVA-asthma models, MIF inhibitor 4-IPP prevented AHR and airway remodeling by inhibiting Drp1 activation and Drp1-dependent mitochondrial fission." (PMID 37674165, 2023). "Similarly, there have been several studies using mouse or rat models of asthma that showed increase in MIF with increased Th-2 cytokines and IgE levels, airway hyperresponsiveness, and airway smooth muscle thickness." (PMID 35420997, 2022). "Collectively, our results suggest that osthole ameliorates macrophage activation in asthma by suppressing the NF-ĸB/MIF signaling pathway, and might be a potential agent for treating asthma." (PMID 33828480, 2021). "The inhibitive effects of osthole in an experimental model of asthma may be mediated by the NF-ĸB/MIF signaling pathway." (PMID 33828480, 2021). "Interestingly, recent studies have demonstrated that MIF induces resistance to glucocorticoids in severe neutrophilic asthma, highlighting the potential of targeting MIF as a therapeutic strategy to enhance glucocorticoid responsiveness and alleviate inflammation in severe asthma." (PMID 39337534, 2024). "However, MIF inhibition should be further evaluated and personalized as a therapeutic option, considering that MIF’s association with asthma is particularly linked to Th2-related responses rather than classic Th1 inflammation." (PMID 39337534, 2024). "Understanding the intricate roles of WISP1 and MIF in the pathogenesis of chronic respiratory diseases such as asthma and COPD could lead to the identi-fication of novel targets for therapeutic intervention to alleviate disease severity and enhance patient outcomes." (PMID 39337534, 2024). "Thus, targeting MIF may represent a promising therapeutic strategy for managing severe neutrophilic asthma by enhancing glucocorticoid responsiveness and mitigating inflammation." (PMID 39337534, 2024). "Existing studies have shown that the levels of MIF in BALF, induced sputum, and serum were found to be significantly elevated in individuals with asthma compared to the control group." (PMID 39176391, 2024). "However, they did not observe an association between other MIF alleles and asthma incidence." (PMID 27598332, 2016).
asthma (continued). "In experimental asthma models, mice lacking MIF exhibit reduced pulmonary inflammation and decreased airway hyperresponsiveness compared to their wild-type counterparts." (PMID 41159021, 2025). "Moreover, the MIF-specific suicide substrate and irreversible inhibitor 4-IPP effectively alleviated airway hyperresponsiveness and remodeling in OVA-induced asthma models by repressing aberrant mitochondrial fission-mediated autophagy activation." (PMID 39337534, 2024). "In the present study, we found that MIF significantly reduced E-cadherin protein level in ASMCs through Drp1-mediated autophagy, and pharmacological inhibition of autophagy restored the decreased E-cadherin protein level in OVA-induced asthma model of rats." (PMID 37674165, 2023). "The first small molecule MIF inhibitor to be described is ISO-1, which binds to the MIF tautomerase active site and inhibits downstream signaling and has been shown to inhibit OVA and HDM-induced airway remodeling in a mouse model of asthma." (PMID 37674165, 2023). "On the other hand, MIF inhibitor 4-IPP and Drp1 inhibitor Mdivi-1 treatment decreased autophagy activity in rat lung tissues, and significantly alleviated airway remodeling in the OVA-asthma model." (PMID 37674165, 2023). "We demonstrated that MIF increased Drp1 phosphorylation through the activation of the ERK1/2 signaling pathway, which subsequently stimulated autophagy activation and further led to the downregulation of E-cadherin, ultimately promoting the proliferation of ASMCs and airway remodeling in asthma." (PMID 37674165, 2023). "The present study provides novel insights that MIF promotes airway remodeling in asthma by activating autophagy and degradation of E-cadherin via ERK/Drp1 signaling pathway, suggesting that targeting MIF/ERK/Drp1 might have potential therapeutic value for the prevention and treatment of asthma." (PMID 37674165, 2023). "In addition, the application of MIF-specific suicide substrate and irreversible inhibitor 4-IPP effectively alleviated airway hyperresponsiveness and airway remodeling in OVA-induced asthma model rats by repressing aberrant mitochondrial fission-mediated autophagy activation." (PMID 37674165, 2023). "In addition, MIF promotes the proliferation and migration of airway smooth muscle cells (ASMCs) by triggering ERK1/2 and FAK signaling pathways and may enhance airway remodeling in asthma by promoting autophagy of ASMCs." (PMID 38145300, 2024). "The median concentration in LC patients compared to healthy non-smokers, asthma sufferers, and smokers was more than 200% higher in SAA (771%), MMP-9 (743%), IL-8 (535%), CXCL9/MIG (482%), TNFRI (406%), Gro (331%), MPO (300%), Rantes (274%), Resistin (271%), TNFRII, and MIF (219%)." (PMID 32085733, 2020).
gastric cancer (40 papers, 2007 to 2025). A primary or metastatic malignant neoplasm involving the stomach. "Many investigations highlighted the role of MIF in gastric cancer, which considered as one of the most leading causes of cancer-related fatalities." (PMID 41159021, 2025). "MAPK4 depletion in gastric cancer cells induces the secretion of macrophage migration inhibitory factor (MIF) to polarize tumor-associated macrophages (TAMs) in orthotopic xenograft tumors." (PMID 36797541, 2023). "A Chinese study investigated the associations between the polymorphisms of interleukin-8 (IL-8), macrophage migration inhibitory factor (MIF) genes, and premalignant gastric conditions in a high-risk area for gastric cancer." (PMID 34071181, 2021). "The progressive increase of epithelial and serum MIF levels in H. pylori, was associated with gastritis, intestinal metaplasia, and gastric cancer, respectively." (PMID 30742638, 2019). "Increased epithelial and serum expression of MIF in gastric cancer suggest its diagnostic and prognostic role in gastric cancer." (PMID 30742638, 2019). "Since we previously showed that HS738 produce MIF in response to H. pylori as a potential link between inflammation and gastric cancer, here we further examined tumor associated fibroblasts for production of MIF." (PMID 24887129, 2014). "We have assayed HNPs and MIF by enzyme-linked immunosorbent assay (ELISA) in tissue and serum to assess their potential as gastric cancer biomarkers." (PMID 19550422, 2009). "As a biomarker, MIF demonstrates diagnostic and prognostic utility for gastric cancer." (PMID 41159021, 2025). "Similarly, MIF was found to be a possible diagnostic marker for gastric cancer at a cut-off value of 3.23 ng/mL with 83.5% sensitivity, 92.3% specificity, and 89.7% accuracy." (PMID 38916819, 2024). "However, the role of MIF in the context of H. pylori infection, which is one of the most important causes of gastric cancer, has yet to be investigated." (PMID 30742638, 2019). "In an investigation it was found that, gastric cancer cells’ pro-angiogenic activity is inhibited by microRNA-1228 via binding to MIF and decreasing its expression." (PMID 41159021, 2025). "For instance, it was found that elevated MIF levels in gastric cancer boosted and improved the angiogenesis process." (PMID 41159021, 2025). "Further research and investigations are needed to fill up the large knowledge scarce regarding MIF as a therapeutic target in gastric cancer." (PMID 41159021, 2025). "Elevated MIF tumor detection in gastric cancer also correlate with angiogenesis, lymph node metastasis, and advanced disease." (PMID 38732068, 2024). "Transcriptomic analysis of CagA+ gastric carcinomas revealed MIF secretion in the TME induces TAM polarization, EMT, and suppression of MAPK4 pathways, all of which are correlated with poor prognosis." (PMID 38732068, 2024). "In this study, we found that MAPK4 interacts with and phosphorylates MIF to promote its ubiquitination and degradation in gastric cancer cells." (PMID 36797541, 2023). "The downregulation of MAPK4 in gastric cancer cells increases MIF secretion to promote macrophage polarization, which facilitates gastric cancer liver metastasis." (PMID 36797541, 2023). "Taken together, these results imply that the downregulation of MAPK4 in gastric cancer cells enhances MIF secretion to activate TAMs, which increases gastric cancer cell invasion and liver metastasis." (PMID 36797541, 2023). "The depletion of MAPK4 in gastric cancer cells induced the secretion of macrophage migration inhibitory factor (MIF) to polarize TAMs in orthotopic xenograft tumors." (PMID 36797541, 2023). "Our data showed that the depletion of MAPK4 significantly increased the expression of MIF in gastric cancer cells and the percentage of CD206-positive macrophages in orthotopic tumors." (PMID 36797541, 2023).
gastric cancer (continued). "In this coculture system, the downregulation of MIF in MAPK4-depleted BGC-823 cells not only robustly inhibited MIF secretion but also significantly suppressed Arg1 expression in BMDMs and gastric cancer cell invasion." (PMID 36797541, 2023). "It has been reported that MIF levels are increased in gastric cancer, and regulate lncZFPM2‐AS1 to promote the development of gastric cancer." (PMID 35567291, 2022). "Diverse mechanisms by which ZFPM2-AS1 modulates cancer progression have been well revealed, including stabilizing MIF in gastric cancer and sponging miR-18b-5p to regulate VMA21 expression in lung adenocarcinoma." (PMID 32065218, 2020). "Among these targets, MIF was reported by another group as a direct target of miR-451a, and its expression was shown to enhance cancer cell growth and invasion in gastric cancer and nasopharyngeal cancer." (PMID 30813343, 2019). "All of the gastric cancer samples exhibited more than 2-fold increase in MIF gene expression while 27 of 30 colon cancer samples exhibited greater than 2-fold increase in MIF gene expression." (PMID 24887129, 2014). "In our present report, we verified MIF as a direct target of miR-451 using luciferase reporter gene assay, which was consistent with the finding in gastric cancer." (PMID 24138931, 2013). "Antibody arrays detect macrophage migration inhibitory factor (MIF) as elevated in the serum of gastric cancer patients." (PMID 19550422, 2009). "Proteomic analyses of serum and tissue samples from patients with gastric cancer and appropriate controls have shown HNPs 1–3 and MIF as elevated in gastric cancer." (PMID 19550422, 2009). "The tissue concentration of MIF, as determined by ELISA, was also elevated in gastric cancer tissue than in adjacent normal gastric mucosa (median fold change=1.33), although not statistically significant (P=0.082, paired Wilcoxon's test)." (PMID 19550422, 2009). "Proteomic analyses of serum and tissue indicate that HNPs 1–3 and MIF have potential as biomarkers for gastric cancer." (PMID 19550422, 2009). "Macrophage migration inhibitory factor (MIF) was increased five-fold (P=1.84 × 10−7) in the serum of gastric cancer patients relative to individuals with benign gastric disease." (PMID 19550422, 2009). "The median concentration of MIF in gastric cancer patients’ serum was 1933 pg ml−1 compared with 414 pg ml−1 for the non-cancer controls (P=1.84 × 10−7, Wilcoxon's test)." (PMID 19550422, 2009). "In gastric cancer and head and neck squamous cell carcinoma patients, MIF levels were elevated in the plasma from patients with accelerated cancer progression, and plasma-MIF concentration correlated negatively with response to immune-checkpoint inhibition." (PMID 39908652, 2025). "In orthotopic mouse models, MAPK4 downregulation in gastric cancer cells increases MIF secretion to activate TAMs, which activates cancer cell EMT to further inhibit MAPK4 expression, and these findings suggest a positive feedback loop between gastric cancer cells and TAMs to drive liver metastasis." (PMID 36797541, 2023). "Nevertheless, the mechanism of MIF stability regulation and the role of MIF in gastric cancer metastasis remain unclear." (PMID 36797541, 2023). "It suggested the potential role of MIF as a biomarker of gastric cancer." (PMID 30742638, 2019). "In addition, ZFPM2-AS1 protected MIF from degradation, increased MIF expression, facilitated gastric cancer proliferation, and inhibited apoptosis." (PMID 31777603, 2019).
gastric cancer (continued). "In particular MIF may be useful, either alone or in combination with other markers, for diagnosing and monitoring gastric cancer." (PMID 19550422, 2009). "We now report that this is also the case in patients from Japan, a country with one of the highest incidences of gastric cancer in the world, and add to the body of evidence that MIF may be a useful biomarker for gastric cancer." (PMID 19550422, 2009). "As with HNPs 1–3, MIF may lack specificity for gastric cancer as it has been reported as elevated in the plasma of patients with ulcerative colitis and Crohn's disease." (PMID 19550422, 2009). "Human neutrophil peptides 1–3 are substantially elevated in gastric cancer tissue (as shown by SELDI tissue analysis and confirmed by ELISA and ELISA) and MIF is substantially elevated in the serum of gastric cancer patients (as shown by antibody array analysis of serum and confirmed by ELISA)." (PMID 19550422, 2009). "Furthermore, our data suggest that serum MIF is elevated in the early stages of gastric cancer relative to relevant disease control subjects, a factor that is of considerable importance in establishing a useful diagnostic role for this potential biomarker." (PMID 19550422, 2009). "Thus, as observed in prostate and gastric cancer, MIF/CD74 interactions appear to play a role in breast tumourigenesis." (PMID 19602265, 2009). "Most of the cytokines measured did not vary substantially between the three pooled samples, but the levels of MIF in this semi-quantitative assay were ∼2-fold increased in early-stage gastric cancer and ∼4-fold in late-stage gastric cancer compared with the control pool." (PMID 19550422, 2009). "Similarly, it was shown that MIF in gastric cancer increase invasion and lymph node metastasis." (PMID 41159021, 2025). "High-expression MIF CATT7 genotypes have been associated with gastritis and gastric cancer in younger patients, suggesting this MIF risk polymorphism may drive early stages of mucosal inflammation and increase the subsequent risk for gastric cancer." (PMID 38732068, 2024). "In particular, serum MIF is highly elevated in the potentially curable early stages of gastric cancer thus warranting further studies to validate this candidate biomarker as a blood test for gastric cancer, either on its own or as part of a panel of biomarkers." (PMID 19550422, 2009). "Additionally, miR-1228 via the downregulation of the macrophage migration inhibitory factor (MIF) serves as a negative regulator of gastric-cancer growth and angiogenesis, supporting its use as a potential therapeutic target for anti-angiogenic therapy against gastric cancer." (PMID 38542354, 2024). "To determine the mechanism through which MAPK4 inhibits MIF secretion in gastric cancer cells, we examined the effects of MAPK4 expression on the protein or mRNA levels of MIF." (PMID 36797541, 2023). "Increased miR-451 expression downregulates macrophage migration inhibitory factor (MIF), a multipotent cytokine with regulatory roles in inflammatory processes, in tumor biopsies of gastric cancer patients." (PMID 32775466, 2020). "Baseline tissue mRNA expression of MIF, Atg5, LC3A and LC3B was measured by real-time PCR in 453 patients (control 165, gastric dysplasia 82, and gastric cancer 206)." (PMID 30742638, 2019). "In conclusion, our proteomic analyses of tissue and serum from gastric cancer patients have shown MIF, HNPs 1–3 and fragments of ITIH4 as potential biomarkers for gastric cancer." (PMID 19550422, 2009).